IL31 (interleukin 31)
Diseases named in the same sentence as IL31 in open-access papers (continued):
Sharing a sentence is not in itself a finding about the gene and the disease.
atopic dermatitis (continued). "Cytopoint®, a caninized monoclonal anti-IL-31 antibody, has been shown to be effective for the treatment of dogs against allergic dermatitis and atopic dermatitis." (PMID 35928119, 2022). "The caninized anti-IL31 Ab, also known as lokivetmab, has been granted a conditional license for use in improving canine atopic dermatitis." (PMID 34451958, 2021). "The notable heterogeneity in IL-31 levels, ranging from >1,000 pg/mL among patients with atopic dermatitis to <200 pg/mL in other diseases, requires additional explanation, and further research is clearly warranted." (PMID 33644103, 2021). "Although most studies predominantly focused on patients with atopic dermatitis (AD), a few studies investigated IL31 in CTCL patients as well." (PMID 34027133, 2021). "For example, IL-22, IL-23, IL-31, and IL-33 were increased in the skin of patients and model animals with allergic dermatitis, AD, and psoriasis." (PMID 33708782, 2021). "Elevated levels of IL-31 or its receptor have been reported in the tissue or serum of patients with pruritic skin diseases, such as atopic dermatitis, prurigo nodularis, and psoriasis." (PMID 33644103, 2021). "The authors reported that the mean circulating IL-31 level was 8798 fg/mL for cats with allergic dermatitis compared to 205 fg/mL in age-matched controls." (PMID 34357916, 2021). "In humans, enhanced IL‐31 expression is positively correlated with the pathogenesis of allergic skin disorders, including atopic dermatitis and allergic contact dermatitis." (PMID 32648940, 2021). "Continuous scratching behaviors are observed in IL-31 transgenic mice, which results in the development of atopic dermatitis-like skin lesions." (PMID 33924978, 2021). "The first human studies using humanized antibodies targeting IL‐31RA, the ligand‐binding subunit of the heterodimeric IL‐31 receptor complex, showed that blocking IL‐31 signaling significantly improves pruritus in patients with atopic eczema." (PMID 32648940, 2021). "In preclinical studies, mice treated with IL-31 exhibited skin lesions and scratching behavior similar to those seen in atopic dermatitis, and treatments targeting IL-31 were found to reduce scratching." (PMID 33644103, 2021). "DOCK8 loss-of-function mutations lead to a combined immunodeficiency with elevated serum levels of IgE, eosinophilia, decreased number of B and T cells as well as severe atopic dermatitis with increased IL-31 expression." (PMID 33644104, 2021). "In patients with psoriasis, similarly to atopic dermatitis, the levels of IL-4 and IL-31 were significantly elevated in comparison to healthy controls." (PMID 33467067, 2021). "More specifically, circulating IL-31 levels in cats with a presumptive diagnosis of allergic dermatitis have been reported to be significantly higher than those of normal cats." (PMID 34357916, 2021). "Interleukin-31 (IL-31) is involved in excessive development of cutaneous sensory nerves in atopic dermatitis (AD), leading to severe pruritus." (PMID 33539470, 2021). "Recently, several studies have indicated that IL-31 is importantly related to atopic dermatitis, and that production of IL-31 is increased by IL-4." (PMID 34959939, 2021). "Interleukin (IL)-31 is a well-known Th2-cell-derived cytokine involved in promoting skin disorders and regulating allergic diseases such as atopic dermatitis (AD)." (PMID 34064490, 2021). "In accordance with this, intervention in the binding of IL-31 to its specific receptor IL-31RA/OSMRβ by specific antibodies has been proven to inhibit the pruritus in atopic dermatitis and prurigo nodularis." (PMID 33924978, 2021). "Patients with early-onset psoriasis have greater levels of Il-31 gene induction compared with healthy controls, and even compared with patients with atopic dermatitis." (PMID 33644103, 2021).
atopic dermatitis (continued). "It is known that both IL-31 and IL-33 initiate skin inflammation and lead to the dysregulation of immunomodulatory proteins in atopic dermatitis through STAT3 pathway activation." (PMID 32566105, 2020). "There is mounting evidence showing that IL-31 is correlated with the itchy pathophysiology of atopic dermatitis, cutaneous T-cell lymphoma, uremic pruritus, allergic contact dermatitis and chronic urticaria." (PMID 32324792, 2020). "Of these, IL-31 is a chief pruritogenic agent in canine atopic dermatitis, but its role in intertrigo remains undefined." (PMID 32760092, 2020). "Interleukin-31 (IL-31) is one of cytokines that induce itch, and has also been shown to play a role in atopic dermatitis." (PMID 33182442, 2020). "In conclusion, the current results suggest that apigenin has the potential to prevent inflammatory diseases, including alleviating compound 48/80-induced atopic dermatitis itch, through its modulation of IL-31 cytokine." (PMID 30987029, 2019). "Interleukin-31 (IL-31) is important in the pruritus of atopic dermatitis and it also participates in the itch of cutaneous lymphoma." (PMID 31619965, 2019). "IL-31 is involved in the pathophysiology of itching, a characteristic finding patients with atopic dermatitis suffer from." (PMID 31028434, 2019). "The cytokine was not only found to induce severe pruritus in mice, where levels of IL-31 correlated with scratching behavior, but a NC/Nga mouse model of atopic dermatitis demonstrated the potential therapeutic benefit of blocking anti-IL-31 antibodies." (PMID 31281316, 2019). "Intriguingly, a monoclonal antibody targeting IL-31 is currently under clinical investigation in atopic dermatitis." (PMID 31244841, 2019). "Aside from the role of IL-31 in atopic dermatitis, it is believed that IL-31 plays a role in inflammatory bowel disease and airway hypersensitivity." (PMID 30987029, 2019). "This seems to apply to humans too, where IL-31 levels were shown to correlate with disease severity in atopic dermatitis." (PMID 31281316, 2019). "Increased levels of IL-31 have now been shown in various inflammatory skin diseases including prurigo nodularis, atopic dermatitis, contact eczema, chronic spontaneous urticaria (CsU), as well as in a subset of patients with mastocytosis." (PMID 31281316, 2019). "Several studies have demonstrated an over-expression of IL-31 in the skin of different pruritic dermatoses, including atopic dermatitis, psoriasis, cutaneous T-cell lymphomas, nephrogenic pruritus, and mastocytosis." (PMID 31244841, 2019). "IL-31 was reported to be increased in specimens from patients with atopic dermatitis, and IL-31-transgenic mice develop atopic dermatitis-like skin inflammation, which is involved in the pathogenesis of atopic dermatitis." (PMID 29703903, 2018). "Histamine induces IL-31 production, which plays an important and crucial role in pruritus and skin barrier function in allergic dermatitis." (PMID 30150993, 2018). "Administration of anti-IL-31 or anti-IL-31RA neutralizing Ab resulted in attenuation of scratching behavior, but not the severity of skin inflammation, in mice that developed atopic dermatitis-like skin inflammation." (PMID 29703903, 2018). "Administration of an H1R antagonist decreased IL-31 levels in the serum of atopic dermatitis patients." (PMID 30150993, 2018). "On the other hand, it is possible that the increased expression of IL‐31 during 1 h of incubation is due to the atopic eczema present in all the allergic patients." (PMID 29992767, 2018). "Treatment of mice that developed atopic dermatitis-like skin inflammation with anti-IL-31 or anti-IL-31RA neutralizing Ab resulted in attenuation of scratching behavior, but not the severity of skin inflammation." (PMID 29703903, 2018).
atopic dermatitis (continued). "For example SDC-4 (syndecan-4) mRNA levels were increased in atopic dermatitis compared with normal skin samples and the inflammatory mediators IL-17, IL-20, IL-24, IL-31, and IL-33 were also elevated in atopic dermatitis." (PMID 29383128, 2017). "The expression of IL-31 has been shown to be correlated with the expression of the Th2 cytokines IL-4 and IL-13 in human skin diseases, and serum IL-31 has been shown to be higher in patients with atopic dermatitis." (PMID 28428802, 2017). "A variety of endogenous pruritogens, such as histamine, serotonin, IL31 and leukotrienes, have been reported to be directly involved in chronic itch, including atopic dermatitis and dry skin diseases." (PMID 28701920, 2017). "The heterodimeric receptor consisting of IL31ra and Osmr has been reported to mediate itch evoked by interleukin-31 (IL31), which is involved in atopic dermatitis." (PMID 28701920, 2017). "Results of investigations conducted during past years, mainly among patients with atopic dermatitis, prurigo, chronic urticaria, and psoriasis, confirmed important role of IL-31 in pathogenesis of itch." (PMID 28808661, 2017). "Another study using an IL-31-induced atopic dermatitis model also showed decreases in inflammation and itching in TRPV1 knockout mice." (PMID 26700618, 2016). "IL-31 is upregulated in allergic and inflammatory diseases, including atopic dermatitis, asthma, cutaneous T-cell lymphomas, and allergic rhinitis, as well as autoimmune diseases such as systemic erythematosus." (PMID 27556734, 2016). "Overexpression or administration of recombinant mouse IL-31 (rIL-31) in mice triggered a skin phenotype that in many ways resembled atopic dermatitis (AD)." (PMID 27556734, 2016). "Several pruritic diseases have been associated with increased levels of Th2 cytokines (for review, see17), and interleukin-31 (IL-31) in particular has been identified as an “itchy” cytokine in atopic eczema." (PMID 27610225, 2016). "Based on the nature of its main producing cells, IL-31 is considered a Th2 cytokine, its involvement having also been predominantly described firstly in respiratory hypersensitivity and in atopic dermatitis." (PMID 26449657, 2015). "Generally, accumulating evidence supports a pathophysiological role of IL-31 in atopic dermatitis and other allergic diseases, however its exact mechanisms have not been finally resolved yet." (PMID 22853438, 2012). "We included the type 2 cytokine IL-13 in our study because IL-31 mRNA expression in skin samples of patients with atopic dermatitis or allergic contact dermatitis was reported to be correlated with IL-13 levels." (PMID 22853438, 2012). "IL-31 transgenic mice, shows pruritis and dermatitis (with an inflammatory cell infiltrate rich of T lymphocytes similar to that observed in atopic dermatitis) with lesions in the skin and dorsal root ganglia." (PMID 18315837, 2008). "Due to the pivotal role of IL-31 signalling in the pathogenesis of itch, this cytokine represents a promising therapeutic target for the treatment of chronic inflammatory skin diseases, including atopic dermatitis." (PMID 41002407, 2025). "One study, for instance, identified that IL-31—a cytokine associated released by activated TH2 cells—was present in skin lesions of patients with atopic dermatitis and ACD, but not psoriasis." (PMID 40078968, 2025). "Atopic dermatitis (AD) is a chronic inflammatory skin disease characterized by epidermal barrier dysfunction and immune dysregulation, with interleukin (IL)-4, IL-13, and IL-31 recognized as key mediators." (PMID 40364058, 2025). "While CSU and atopic dermatitis (AD) can be clinically distinguished by specialist clinicians, they share significant similarities in their inflammatory mechanisms, particularly in the role of pro-inflammatory cytokines like IL-4, IL-5, IL-13, and IL-31." (PMID 38396704, 2024).
atopic dermatitis (continued). "Many serological changes are identified in atopic dermatitis (AD), including elevated blood levels of total IgE, chemokines produced from macrophages, a chemokine that is activated and regulated by the thymus, IL-31, and a chemokine that stimulates cutaneous T cells." (PMID 38731996, 2024). "In addition, IL31 is known as the mediator of pruritus and has been shown to be elevated in atopic dermatitis and psoriasis." (PMID 36982700, 2023). "In addition, we used oclacitinib, an oral JAK inhibitor registered for the treatment of canine allergic dermatitis, to successfully ameliorate intradermal IL-31-induced pruritic behaviors in this study and validate the model." (PMID 37235412, 2023). "IL-31 has an important role in inducing atopic dermatitis and pruritus in several species." (PMID 37627467, 2023). "The mean serum IL-31 level in dogs with SRMA (n = 18) was mildly higher compared to dogs with atopic dermatitis (n = 3, p = 0.8135) and MUO (n = 15, p = 0.7618) and markedly higher than in healthy controls (n = 10, p = 0.1327) and dogs with infectious meningoencephalitis (n = 3, no statistics)." (PMID 37627467, 2023). "However, antimicrobial peptides have been reported to induce the IL-4, IL-13, and IL-31 inflammatory pathways, which are hallmark features of atopic dermatitis, indicating that these peptides might function as a double-edged sword in the pathogenesis of atopic dermatitis." (PMID 37298299, 2023). "In addition, oclacitinib, an oral JAK inhibitor registered for the treatment of canine allergic dermatitis, successfully reduced the intradermal IL-31-induced pruritic behaviors in this study." (PMID 37235412, 2023). "Nemolizumab is an anti-IL-31 RA humanized monoclonal antibody that rapidly reduces itch in atopic dermatitis patients, with sustained efficacy, shows a suitable safety profile and decreases the itch–scratch cycle associated with AD patients, improving their quality of life." (PMID 36839897, 2023). "In primary keratinocytes, atopic dermatitis cytokines (IL-4, IL-13 and IL-31) significantly decreased mRNA expression of the barrier structure protein filaggrin (FLG) without histamine (0.3 ± 0.06-fold, p < 0.001) and in combination with histamine (0.24 ± 0.04-fold; p < 0.001)." (PMID 36615633, 2023). "Research suggests that H4R, by activating Th2 cells and producing IL-31, may trigger the development of allergic dermatitis." (PMID 36295796, 2022). "IL-31 is a known marker of itch in type 2 inflammatory diseases such as atopic dermatitis and PN." (PMID 36561717, 2022). "The role of IL-31 in PN and atopic dermatitis has been investigated." (PMID 36561717, 2022). "In this respect, IL-31 has received much attention for its role in canine atopic dermatitis." (PMID 34357916, 2021). "Indeed, previous studies have shown increased expression of IL-31 in Th2-dominant diseases such as allergic asthma, atopic dermatitis, and cutaneous T-cell lymphoma, where IL-31 overexpression is associated with Th2 responses." (PMID 34642338, 2021). "There were attempts to treat atopic dermatitis by blocking IL-31 or IL-31 receptor." (PMID 34064490, 2021). "In clinical studies, levels of serum IL-31 have been found to be elevated in patients with atopic dermatitis, compared with healthy individuals, and decreased after cyclosporin treatment; furthermore, IL-31 levels were shown to correlate with disease severity and pruritic symptoms." (PMID 33644103, 2021). "Among these pruritogens, particular attention has been paid to interleukin-31 (IL-31), since systemic administration of the anti-IL-31 receptor A (IL-31RA) antibody nemolizumab successfully ameliorates chronic itch in patients with atopic dermatitis and prurigo nodularis." (PMID 33924978, 2021). "Moreover, in canine atopic dermatitis, anti-canine IL-31 antibody (lokivetmab) significantly inhibited scratching in dogs with canine atopic dermatitis." (PMID 33924978, 2021).
atopic dermatitis (continued). "Additionally, lokivetmab (an injectable anti-canine interleukin-31 [IL-31] monoclonal antibody) has been used as a new treatment option for atopic dermatitis (AD)." (PMID 34926639, 2021). "Recent studies found pruritic skin inflammation in transgenic mice overexpressing IL31 and demonstrated significantly elevated serum and mRNA IL31 levels in atopic dermatitis (AD) and prurigo nodularis suggesting a role for IL31 in the pathogenesis of pruritic skin diseases." (PMID 34027133, 2021). "IL-31 is involved in pruritus in atopic dermatitis (AD) and the pathogenesis of AD." (PMID 34064490, 2021). "Other cytokines, such as IL-4, IL-13, IL-31 and IL-33 play a key role in the pro-inflammatory and anti-inflammatory signaling pathways in patients suffering from inflammatory skin diseases such as psoriasis or atopic dermatitis." (PMID 33467067, 2021). "Induction of IL-31 is a prominent factor in the development of atopic dermatitis in dogs." (PMID 32377529, 2020). "In addition, IL-31 was also found to play a significant role in pruritus (itch) in atopic dermatitis." (PMID 30987029, 2019). "Similarly, the anti-canine-IL-31 monoclonal antibody, lokivetmab, has been used to treat atopic dermatitis in dogs." (PMID 31281316, 2019). "Indeed, we observed increased IL-31 serum levels in CsU patients, although these levels were generally lower than those seen in atopic dermatitis patients." (PMID 31281316, 2019). "Studies carried out in mouse models as well as data obtained from the analysis of sera and biopsies from patients with atopic dermatitis (AD) indicate that IL-31 is involved in the pathogenesis of allergic skin inflammatory diseases and is upregulated in these diseases." (PMID 30647024, 2019). "Besides atopic dermatitis, IL‐31 has also been shown to be increased in nasal secretions following nasal allergen challenge in allergic rhinitis patients." (PMID 29992767, 2018). "IL-31 has been described to play a key role in the pathogenesis of atopic dermatitis." (PMID 26956917, 2016). "Several studies documented the importance of IL-31 in pruritus observed in atopic dermatitis (AD)." (PMID 25756056, 2015). "Numerous studies indicate that IL-31 may play a role in development of many dermatoses i.e., atopic dermatitis, allergic contact dermatitis, chronic urticaria and prurigo nodularis." (PMID 23108364, 2013). "Over-expressed IL-31 could induce pruritus and skin dermatitis resembling human atopic dermatitis (AD) in mice." (PMID 22272250, 2012). "Several studies support a role for IL-31 in atopic dermatitis and other epithelial pathologies." (PMID 22853438, 2012). "Importantly, the expression of IL-31 is increased in the skin of patients with atopic dermatitis and correlates with IL-4 and IL-13 expression." (PMID 18315837, 2008). "One possibility is that IL-31 blockade induces compensatory upregulation of Th2 cytokines such as IL-4 and IL-13, which could partly explain the development or exacerbation of eczematous lesions, including atopic dermatitis." (PMID 41464561, 2025). "Moreover, the serum level of IL-31 was elevated in patients with atopic dermatitis." (PMID 35324695, 2022). "The receptors for IL-31, IL-31RA, and the receptor for IL-33, ST2, are commonly expressed on dermal fibroblasts, and it is speculated that IL-31 and IL-33 can synergistically stimulate basophils that interact with fibroblasts to release atopic dermatitis (AD)-related chemokines." (PMID 35634336, 2022). "In addition, IL-31-expressing T cells are increased in the lesional skin of atopic dermatitis." (PMID 33924978, 2021). "Recently, Interleukin (IL)-31 and its receptor complex attracted significant interest, as clinical phase two studies demonstrated therapeutic efficacy of the neutralizing IL-31 receptor A (IL-31RA) antibody nemolizumab in patients suffering from atopic dermatitis or prurigo nodularis." (PMID 33644104, 2021).